ENSG00000253041
Gene: Small nucleolar RNA gene on chromosome 9 (101,322,477 to 101,322,533, forward strand). Ensembl gene ENSG00000253041.
Homologues: Paralogues in human: SNORA31B (84% identical), SNORA31 (79% identical).